MSLN (mesothelin)
Diseases named in the same sentence as MSLN in open-access papers (continued):
Sharing a sentence is not in itself a finding about the gene and the disease.
ovarian carcinoma (continued). "The most common target antigens in ovarian cancer CAR-T include MUC16, mesothelin, HER2 and folate receptor α (FRα)." (PMID 35941287, 2022). "Several studies reported that co-expression of mesothelin and CA125 correlated with aggressive features of tumors and poor prognosis of several carcinomas such as ovarian carcinomas." (PMID 33832498, 2021). "Mesothelin (MSLN), a glycoprotein normally expressed by mesothelial cells, is overexpressed in ovarian cancer (OvCa) suggesting a role in tumor progression, although the biological function is not fully understood." (PMID 34830322, 2021). "Biomarker proteins known to be overexpressed in serum from ovarian cancer patients, such as CA125 (MUC16), HE4, and mesothelin, were found in the biospecimens." (PMID 33413078, 2021). "Both mesothelin and LRG have been used in combination with CA125 to improve ovarian cancer detection; both proteins have also been detected in urine of ovarian cancer patients." (PMID 33413078, 2021). "Mesothelin (MSLN) is a cell-surface glycoprotein and tumor differentiation marker expressed in several tumors, including lung cancer, pancreatic cancer, ovarian cancer, and MPM." (PMID 34064074, 2021). "More than 2000 proteins were expressed in each of the three biospecimens, including several known ovarian cancer biomarkers such as CA125, HE4, and mesothelin." (PMID 33413078, 2021). "Only mesothelin and HE4 showed high specificity, and it is clinically important that these markers are upregulated in serum ovarian cancer." (PMID 34439871, 2021). "In order to reversibly alter possible MSLN-specific phenotypes, we lentivirally transduced either MSLNlow BG1 and OVCAR4 or ΔMSLN OVCAR8 ovarian cancer cells to overexpress or rescue the full length MSLN, respectively." (PMID 32612258, 2020). "On the active ovarian cancer therapeutic radiopharmaceutical trial (NCT03507452), the mesothelin-targeting thorium-227 conjugate is given every six weeks for a maximum of three cycles." (PMID 32764223, 2020). "An alternative MSLN-targeting CAR therapy has been tested successfully in vitro and in vivo in a mouse model of ovarian cancer." (PMID 32937961, 2020). "Phase I/II clinical trials are currently in progress in order to investigate CAR-T cells targeting MUC16 (NCT02498912), mesothelin (NCT01583686), and NY-ESO-1 (NCT01567891 and NCT02457650) for ovarian cancer." (PMID 33123161, 2020). "The results showed that mesothelin-targeted IVT CAR lymphocytes exerted cytotoxicity in the human K562 erythroleukaemia cell line and in the murine ovarian cancer Defb29/Vegf-a-luc cell line." (PMID 32899932, 2020). "A 227Th-radiolabeled mAb directed against MSLN, the BAY2287411, has recently been assessed in combination with DNA damage response inhibitors using experimental ovarian cancers—this combination revealed a synergistic anti-tumor effect." (PMID 32517181, 2020). "On the basis of the strong in vitro synergy on the ovarian cancer cell line OVCAR-3, we chose this model for in vivo evaluation of the combinations of MSLN-TTC with the PARPi and the ATRi." (PMID 30850485, 2019). "We further explored the combination of MSLN-TTC and ATRi in the OVCAR-8 ovarian cancer xenograft model, which had previously demonstrated in vitro synergy from the ATRi combination." (PMID 30850485, 2019). "It has been shown that MSLN binds to the ovarian cancer biomarker CA125 and this interaction plays a role in the peritoneal metastasis of ovarian cancer." (PMID 30134520, 2018). "The MF-T-induced reduction of surface mesothelin expression was confirmed in endogenously mesothelin-positive NCI-H322 human lung cancer and OVCAR-3 human ovarian cancer cells by flow cytometry." (PMID 30344925, 2018). "Mesothelin (MSLN) is a cell surface glycoprotein that is highly expressed on pancreatic cancer, ovarian cancer, and mesothelioma." (PMID 29614005, 2018). "Hence, blocking MSLN-related pathway may be a potential target for ovarian cancer therapy." (PMID 29393911, 2018).
ovarian carcinoma (continued). "Hypomethylation of the MSLN promoter and transcriptional up-regulation have been suggested in MPM, pancreatic and ovarian carcinoma, but few studies have reported post-transcriptional regulation of MSLN by miRNAs." (PMID 28125734, 2017). "As a tumor marker, soluble mesothelin in serum plays an important role in diagnosing and monitoring therapeutic effect for patients with malignant pleural mesothelioma (MPM) and ovarian cancer." (PMID 28356156, 2017). "A study demonstrated that fully human mesothelin-specific CAR-T cells showed potent cytolytic activity toward mesothelin-positive tumor cells and controlled large, well-established ovarian cancer growth in a xenogeneic mouse model." (PMID 28356156, 2017). "Taking advantage of the high-affinity interaction between mesothelin and the MUC16 biomarker located on ovarian cancer cell membranes, we designed a mesothelin/TR3 fusion protein, and subsequently a more potent and stabilized truncation variant, Meso64TR3." (PMID 29267342, 2017). "To date, three biomarkers as measured in blood plasma or serum are approved by the FDA to screen for ovarian cancer: CA125, HE4, and MSLN." (PMID 26779384, 2015). "Although the literature is sparser than that for MSLN, a few studies have looked at MPF as a biomarker for mesothelioma, ovarian cancer and pancreatic cancer." (PMID 23590973, 2013). "Using the described ECL assays, the serum levels of FRA, MSLN and MPF were measured in samples from 258 ovarian cancers and 60 age-matched controls." (PMID 23590973, 2013). "CA125, HE4 and MSLN have been approved by the United States Food and Drug Administration (FDA) as biomarkers for recurrent ovarian cancer (CA125 and HE4) and diagnosis of mesothelioma (MSLN)." (PMID 23590973, 2013). "Several other markers of ovarian cancer, including MSLN and, to a lesser extent, MPF have been described." (PMID 23590973, 2013). "We therefore chose to develop a similar ECL-based assay for MPF for comparative studies not only to FRA, but to other more accepted markers of ovarian cancer – CA125, MSLN and HE4." (PMID 23590973, 2013). "Serum levels of all biomarkers differed significantly between ovarian cancer and control serum samples, with P values of <0.0001, <0.0001 and 0.0006 for FRA, MSLN and MPF, respectively." (PMID 23590973, 2013). "Evaluate and compare the utility of serum folate receptor alpha (FRA) and megakaryocyte potentiating factor (MPF) determinations relative to serum CA125, mesothelin (MSLN) and HE4 for the diagnosis of epithelial ovarian cancer (EOC)." (PMID 23590973, 2013). "The strong interaction between MUC16 and mesothelin, a glycosylphosphatidylinositol- (GPI-) anchored glycoprotein, promotes cell adhesion and peritoneal metastasis of ovarian cancer cells." (PMID 22481932, 2012). "MSLN and another marker HE4 have been recently studied for their value as markers for detection of ovarian carcinoma." (PMID 22485139, 2012). "Among serum protein markers, HE4 and mesothelin can augment CA125 detection providing higher sensitivity and specificity due to the presence of these proteins in early-stage ovarian cancer." (PMID 21577260, 2011). "Ovarian cancer cells adhere to peritoneal mesothelia via the formation of several compounds: CD44/HA, β1-integrin/fibronectin, CA125/mesothelin, and so on." (PMID 21294926, 2011). "Mesothelin was also shown to possess comparable specificity and sensitivity to CA125 for ovarian cancer diagnosis." (PMID 21577260, 2011). "By serving as a ligand of mesothelin, MUC16 mediates binding between ovarian cancer cells and the mesothelium." (PMID 20497550, 2010). "It was found later that mesothelin interacted strongly and specifically with the large glycoprotein MUC16, which is highly expressed in ovarian cancer cells, and that this interaction was mediated by the N-linked oligosaccharides of MUC16." (PMID 19128473, 2009). "Proteins MSLN and BARD1 are well-known autoantigens of ovarian cancer and have also been found by SEREX." (PMID 18173842, 2008).
ovarian carcinoma (continued). "Moreover, anti-mesothelin CAR Vδ2 T cells are efficacious and safe in subcutaneous and intraperitoneal in vivo ovarian cancer models." (PMID 40148988, 2025). "Anetumab ravtansine, an anti-MSLN ADC, showed an ORR of 27.7% and a median PFS of 5 months in combination with pegylated liposomal doxorubicin in a phase Ib study (NCT02751918) in patients with platinum-resistant epithelial ovarian cancer." (PMID 40722601, 2025). "MSLN promotes the expression of matrix metalloproteinase-7 (MMP-7) through the MAPK/ERK and JNK signaling pathways, thereby enhancing the migration and invasion of ovarian cancer cells." (PMID 39023820, 2024). "Recently, mesothelin-targeted agents, such as the secreted phosphoprotein 1 (SS1P) immunotoxin and anti-mesothelin chimeric antigen receptor (CAR)-T cells, have entered clinical trials for mesothelioma and ovarian cancer." (PMID 38396817, 2024). "Another phase I clinical trial (NCT03608618) evaluated MCY-M11, a mesothelin-directed CAR mRNA transfected into peripheral blood mononuclear cells, in patients with ovarian carcinoma and malignant peritoneal mesothelioma was terminated due to a sponsor shift in focus." (PMID 38667465, 2024). "Mesothelin is upregulated in the bone marrow of one-third of pediatric AML patients and known for its oncogenic properties in solid tumors, including pancreatic and ovarian cancer." (PMID 38396817, 2024). "Combination of MSLN and MUC16 mediated adhesion in ovarian cancer." (PMID 38628720, 2024). "Thus, many additional ADCs against various targets, including NaPi2b, HER2/3, mesothelin, and MUC16, which are expressed in ovarian cancer, are under investigation." (PMID 38539161, 2024). "Our results suggest that ligand-receptor-based CAR T cell therapy that is designed to exploit the interaction between mesothelin and MUC16 may be effective as an ovarian cancer treatment." (PMID 38637885, 2024). "As tumors form, the glycosylphosphatidylinositol-anchored cell-surface protein known as mesothelin binds MUC16 at N-glycosylation sites to promote cancer cell adhesion, leading to metastatic activation of tumors, including mesothelioma and ovarian cancer, in the pleura and peritoneum." (PMID 38637885, 2024). "MSLN has been shown to be overexpressed in mesotheliomas, pancreatic cancers, ovarian cancers, and certain lung cancers and is not expressed in normal human tissues except mesothelial cells at relatively low levels." (PMID 36166071, 2023). "Results showed that LCAR-M23 CAR T cells possessed specific killing property against MSLN-expressing ovarian cancer cell lines (OVCAR-3, CAOV-3, and SK-OV-3), and no cytotoxicity was observed against MSLN-negative cell lines (A-431, K-562, and HEK-293)." (PMID 36166071, 2023). "MSLN expression was detected in ovarian cancer cell lines, OVCAR-3, CAOV-3, and SK-OV-3, whereas no MSLN expression was found in A-431, K-562, and HEK-293 cell lines." (PMID 36166071, 2023). "Indeed, MSLN-based immunotherapies have been proposed for different MSLN-expressing malignancies, such as PDAC itself, ovarian cancer, malignant mesothelioma, and lung adenocarcinoma." (PMID 37760554, 2023). "Both mesothelin and CA125 are overexpressed in approximately 88% of ovarian cancer cases." (PMID 37670338, 2023). "These initial studies found mesothelin in ovarian cancers, mesothelioma and pancreatic cancers, but not lung cancer." (PMID 36911670, 2023). "Eleven trials are about solid tumors (including ovarian cancer, prostate cancer, non-small cell lung cancer, pancreatic cancer, and glioblastoma), in which CAR-NK cells target some over-expressed antigens such as MUC1, PSMA, ROBO1, mesothelin, and HER2." (PMID 36324149, 2022). "Mesothelin is overexpressed in a variety of cancers, including ovarian cancer, but it is also expressed in non-pathological tissues, which can cause off-target effects." (PMID 35941287, 2022).
ovarian carcinoma (continued). "Several generations of immunotoxins, such as SS1P and LMB100, were engineered by conjugation of anti-human MSLN SS1 Ab to PE38 (truncated Pseudomonas exotoxin), and successfully tested in clinical trials in patients with mesothelioma, ovarian cancer and pancreatic cancer." (PMID 36358290, 2022). "Concerning the use of MSLN as a biomarker for the diagnosis of HSOC, a significant amount of data in the literature suggest that this glycoprotein is expressed in different subtypes of ovarian carcinoma, especially HSOCs." (PMID 35565412, 2022). "The hierarchical clustering revealed a group of proteins that have previously been reported to be expressed at elevated levels in ovarian cancer serum samples, including: CA125 (MUC16), HE4, MSLN, MK, KLK8, KLK11, NECT4, FOLR1, as well as KLK13, KLK14, and IL6." (PMID 35804849, 2022). "Targeting MSLN by antibodies or chimeric antigen receptor-modified T (CAR-T) cells and immune checkpoint blockades as well as apatinib, an anti-angiogenic drug, have been used in patients with refractory ovarian cancer." (PMID 33589520, 2021). "However, MSLN expression does regulate MCA size, as mesothelial cells that express MSLN produce larger MCAs when co-cultured with ovarian cancer cells." (PMID 34830322, 2021). "Mesothelin (MSLN)-directed CAR-NK92 cells demonstrated effective elimination of MSLN-expressing cell lines (OVCAR-3 and SKOV3), and of subcutaneous and intraperitoneal ovarian cancer in mice models." (PMID 34072732, 2021). "Anti-MSLN abrogated the DKK1 reduction and increased the apoptosis of ovarian cancer cells." (PMID 33613114, 2021). "Herein, we investigate a high-performance microfluidic detection platform to conduct a novel panel of multiple biomarkers for the early detection of ovarian carcinoma, which include CA125, HE4, OPN, MSLN, Hsp70, CA153, AFP, IL-6, and IL-8 using a microfluidic chip." (PMID 35423342, 2021). "Mesothelin (MSLN), a glycosylphosphatidylinositol (GPI) anchored cell surface protein, is physiologically expressed on mesothelial cells and is overexpressed in several types of tumors, including ovarian cancer." (PMID 34948446, 2021). "Given safety confirmation with transient CAR mesothelin expression, a second phase 1 trial (NCT02159716) was conducted in 15 patients with mesothelioma, ovarian cancer and pancreatic cancer using a lentiviral transduction vector expressing the same murine-based anti-mesothelin second generation CAR." (PMID 32914147, 2020). "Mesothelin is a cell-surface glycoprotein that is expressed at low levels on normal tissues whereas it is overexpressed in the majority of MPM, as well as in lung, pancreatic, and ovarian carcinomas." (PMID 32914147, 2020). "Another antibody–drug conjugate in a clinical trial currently underway for patients with advanced solid tumors including ovarian cancer, uses a mAb targeting MSLN conjugated to a cytotoxic drug BMS-986148 with and without Nivolumab (NCT02341625)." (PMID 32937961, 2020). "Heterotypic (cancer cell to mesothelial cell) interactions of mesothelin (MSLN) and its binding partner MUC16, which is the membrane-bound form of the ovarian cancer serum tumor marker CA-125 are important for attachment of cancer cells to the mesothelial layer." (PMID 32780245, 2020). "Similar heterogeneity in plasma MSLN concentrations among patients with mesothelioma and ovarian carcinoma have partly been attributed to the lack of MSLN expression in their tumors, and/or to differences in the study population." (PMID 31222072, 2019). "Chang and colleagues found that MSLN was present in 10 of 15 nonmucinous ovarian cancers and absent in all 4 mucinous ovarian cancers examined." (PMID 31463062, 2019). "The MUC16-mesothelin interaction is capable of activating MUC16, thus enhancing ovarian cancer cell metastasis and the epithelial mesothelial to mesenchymal transition, suggesting that the binding of these proteins triggers pathways that regulate cellular adhesion and motility." (PMID 31514468, 2019).
ovarian carcinoma (continued). "Mesothelin is frequently co-expressed with and binds to CA125, a well-established ovarian cancer biomarker, and may be involved in the peritoneal spread of ovarian cancer." (PMID 30344925, 2018). "Other molecular interactions supporting peritoneal adhesion are fostered by a glycoprotein on the surface of EOC cells, ovarian carcinoma antigen CA125 (MUC16), and mesothelin expressed on the surface of mesothelial cells, both of which were demonstrated by in vitro studies using EOC cell lines." (PMID 30445726, 2018). "In addition, the binding of mesothelin to CA125, an ovarian cancer biomarker, and upregulation of metalloproteinases has been reported to facilitate metastatic spread, making mesothelin an interesting target in ovarian cancer." (PMID 30344925, 2018). "Efficacy was generally higher in tumors with strong mesothelin expression, while no activity was seen in mesothelin-negative ovarian cancer models." (PMID 30344925, 2018). "Mesothelin is expressed at low levels in normal tissues, including pleura, pericardium, peritoneum, tunica vaginalis, but it is overexpressed in various malignancies including MPM, ovarian cancers, pancreatic cancers, and non-small cell lung cancers." (PMID 28356156, 2017). "Although the physiological role of this protein is still unknown, over-expression of MSLN is often observed in some types of human tumours, namely MPM (Malignant Pleural Mesothelioma), pancreatic and ovarian carcinomas." (PMID 28125734, 2017). "HER2, mesothelin and CA125 are a potential target to these lymphocytes in ovarian cancer." (PMID 29027969, 2017). "Some studies suggest that mesothelin is the receptor of CA125/MUC16, and the interaction between mesothelin-CA125 mediates cell adhesion and may be a critical point in the metastatic of ovarian cancer." (PMID 28356156, 2017). "Anti-mesothelin mAbs react with renal cell carcinomas and pancreatic and ovarian cancers, unlike the JMAM4 mAbs that did not react with lung, ovarian, or renal cell carcinomas or any of the other cancer cell lines tested." (PMID 27342200, 2016). "MSLN may aid in the peritoneal implantation and metastasis of tumors through its interaction with CA125 (also known as MUC16), an ovarian cancer antigen." (PMID 25883990, 2015). "Other serum markers, which include mesothelin, matrix metalloproteinase 7 (MMP7), cytokeratin 19 fragment (CYFRA 21-1), and glycodelin, have shown encouraging performance in ovarian cancer, but mainly in clinical series." (PMID 26819954, 2015). "However, recent studies have shown that mesothelin binds to the cell surface mucin, MUC16 (CA-125), which is commonly used as a marker to follow patients with ovarian cancer." (PMID 25502863, 2015). "Ld1 is an in-house designed H2d-restricted MSLN peptide that did not induce ovarian cancer specific T-cell response in H-2q FVB mice." (PMID 24565018, 2014). "ERK and JNK were also implicated in mesothelin-stimulated migration of ovarian cancer cells, whereas JNK but not ERK or p38 MAP kinase was involved in GnRH-induced ovarian cancer migration." (PMID 25601855, 2014). "Mesothelin binds with high affinity to CA125 through glycan interaction and mediates heterotypic cell adhesion that may be involved in ovarian carcinoma pathogenesis and micrometastatic disease." (PMID 22163010, 2011). "These included i) mesothelin (MSL), a glycosyl-phosphatidyl inositol-anchored membrane glycoprotein ii) human epididymis protein 4 (HE4), a glycoprotein commonly expressed in ovarian tumors and iii) cancer antigen 125 (CA125), the current gold standard tumor marker in ovarian cancer." (PMID 39077473, 2024). "Thus, the collective findings of these investigations indicate that MSLN-CAR NK cells may be effectively employed to eliminate tumor cells, delay ovarian cancer development in vivo and in vitro, and extend the survival of tumor bearing mice." (PMID 38694508, 2024).